TBX3 (T-box transcription factor 3)
Diseases named in the same sentence as TBX3 in open-access papers (continued):
Sharing a sentence is not in itself a finding about the gene and the disease.
liver cancer (7 papers, 2018 to 2025). An epithelial or non-epithelial malignant neoplasm that arises from the liver. "(2007) identified TBX3 as a downstream target gene activated by the Wnt/β‐catenin signalling pathway in liver cancer." (PMID 39403898, 2024). "Given the ongoing debate regarding the role of TBX3 in liver cancer and the limited knowledge of its specific involvement in iCCA, our study aimed to investigate the expression pattern of TBX3 and elucidate its functional role in iCCA." (PMID 38909034, 2024). "They injected Tbx3-expressing human liver cancer cells into mice and saw a positive correlation between Tbx3 activity and cancer progression." (PMID 30151243, 2018). "The intensified Wnt/β-catenin signaling seen in the aged gastric organoids resulting from decreased Dkk3 expression led to induction of the transcription factor Tbx3, which is a Wnt/β-catenin signaling target gene involved in the survival of liver cancer cells." (PMID 36923312, 2022). "This interaction is needed for Tbx3’s tumor-promoting function and may be targetable with drugs in order to prevent metastasis in patients with aggressive liver cancer." (PMID 30151243, 2018). "We quantified the copy numbers of Tbx3 and E-cadherin mRNA in 53 primary liver cancer tissues (HCCs) and their corresponding adjacent non-tumor tissues by RT-qPCR." (PMID 30151243, 2018). "It is tempting to speculate that the ability of these drugs to inhibit TBX2 and TBX3 may be through their inhibition of the Wnt signalling pathway because it has been previously reported to regulate TBX2 in pancreatic and prostate cancer and TBX3 in liver cancer." (PMID 39403898, 2024).
lung carcinoma (7 papers, 2013 to 2024). "On the other hand, our data suggested that the expression of TBX3 in lung cancer was significantly downregulated, which was contrary to Wu’s study." (PMID 38413457, 2024). "Recent evidence has suggested that TBX3 is over-expressed in a number of cancers including lung cancer, as well as in transformed lung fibroblast cells." (PMID 23527081, 2013). "Low expression of TBX3 in lung cancer predicted low survival and poor prognosis of patients, which indicated that TBX3 was an independent prognosis factor and a potential therapeutic target for OS in lung cancer." (PMID 38413457, 2024). "TBX3 might play an inhibitory role in malignancy progression of lung cancer." (PMID 38413457, 2024). "Besides, TBX3 correlated with survival of lung cancer patients." (PMID 38413457, 2024). "The experimental results show that CEP55, NMU, CAV1, TBX3, FBLN1and SYNM have significantly different expression in lung cancer." (PMID 36404510, 2022). "Western blots using up to 25 μg of nuclear extracts showed very little or undetected expression of TBX2, TBX3, and TBX5 in all tested lung cancer cell lines while only HBEC2 cells expressed TBX5 which is consistent with qPCR results." (PMID 30425966, 2018). "Moreover, the lung cancer-specific OS rate significantly increased in patients with TBX2 subfamily high expression group than that in low expression group (TBX2 logrank P = 0.0023, TBX3 logrank P = 1.9e-5, TBX4 logrank P = 0.027, TBX5 logrank P = 2.2e−10)." (PMID 38413457, 2024).
pancreatic cancer (7 papers, 2006 to 2025). "Regarding the relationships of each subfamily of T-box gene and cancer, TBX2 and TBX3 over-expressions were observed in several human cancers, including ovarian, cervical, mammary, liver and pancreatic carcinomas, and current findings revealed its association with malignant behavior." (PMID 33447348, 2020). "In pancreatic cancer, TBX3 activates NODAL/ACTIVIN signaling to promote CSCs self-renewal." (PMID 38965548, 2024). "LSM3 and TBX3 may also participate in cell cycle control; upregulation of LSM3 promotes proliferation of pancreatic cancer cells, and TBX3 may interact with the cell cycle protein CDKN2A." (PMID 17054779, 2006).
hepatocellular carcinoma (6 papers, 2014 to 2025). A malignant tumor that arises from hepatocytes. "The pathway analysis revealed that multiple cancer-related gene lists, such as “Renal cell carcinoma”, “Hepatocellular carcinoma”, and “Cell cycle”, were enriched in TBX3 negatively correlated genes." (PMID 38909034, 2024). "Of note, overlapping genomic occupancy between TBX3 and β-catenin at relevant cancer-inducing genes, such as MYC, RAS, and STAT1 is also found in hepatocellular carcinoma (HCC) cells, both in cell lines (HepG2 from ENCODE) and in two independent patient-derived HCC biopsies (our data)." (PMID 40343989, 2025). "However, the mechanism by which Tbx3 participates in the metastasis of hepatocellular carcinoma (HCC) remains largely unknown." (PMID 30151243, 2018).
prostate carcinoma (6 papers, 2015 to 2025). A carcinoma that arises from epithelial cells of the prostate gland. "Using the DepMap resource, we have shown that one of the identified partners, the TBX3 protein is as critical for the growth and proliferation of prostate cancer cell lines in vitro as HOXB13." (PMID 41164275, 2025). "Further, TBX3 interacts with androgen receptors, playing a key role in the progression and treatment resistance of prostate cancer." (PMID 39897553, 2025). "In promoting proliferation in ART, CREB5 exhibited a strong degree of interaction with known AR transcription machinery, including FOXA1, HOXB13, and GRHL2, as well as novel prostate cancer regulators TBX3 and NFIC." (PMID 35550030, 2022). "Thus, HOXB13 and TBX3 can be considered together as potential targets for the development of specific inhibitors that suppress prostate cancer cell growth." (PMID 41164275, 2025). "Furthermore, upon computing the average dependency scores in DEMETER, we found that NFIC and TBX3 ranked among the strongest dependencies in these prostate cancer cell lines while exhibiting limited overall dependency in the other 495 cell lines." (PMID 35550030, 2022). "Analysis of individual prostate cancer cell lines revealed that knockout of both genes, HOXB13 and TBX3, leads to the death of the same lines: VCaP, LNCaP (clone FGC), PC-3 and 22Rv1." (PMID 41164275, 2025). "To examine the relative contribution of TBX3 and NFIC to cell viability, we analyzed genome-scale RNAi screens performed in eight prostate cancer cell lines as a part of Project Achilles 2.20.1." (PMID 35550030, 2022). "Based on motif enrichment analyses of the TBX3 or NFIC binding sites, we observed statistically significant enrichment of FOXA1 binding motifs identified in experiments on breast or prostate cancer cell lines." (PMID 35550030, 2022). "As examples, TBX3 and NFCI have been previously detected in large-scale proteomic approaches that interrogated prostate cancer tissue." (PMID 35550030, 2022). "This close correlation of TBX3 and NFIC dependency with that observed for FOXA1 supports the conclusion that TBX3 and NFIC regulate prostate cancer cell viability in the AR setting." (PMID 35550030, 2022). "TBX3 and NFIC, two nuclear factors that are amplified or overexpressed in mCRPC, were vulnerabilities in other prostate cancer models, including ones that were ART resistant, and bound to FOXA1 transcription regulatory elements." (PMID 35550030, 2022). "Together, we found TBX3 and NFIC were nuclear proteins associated with CREB5, FOXA1, and functionally impacted prostate cancer cell viability and ART resistance even absent of CREB5." (PMID 35550030, 2022). "Previous research identified four single nucleotide polymorphisms (SNPs) principally associated with circulating PSA levels rather than with prostate cancer risk (TERT rs2736098, FGFR2 rs10788160, TBX3 rs11067228, KLK3 rs17632542)." (PMID 26431041, 2015). "We found that TBX3 and NFIC genomic amplifications together represented up to 13.3% of prostate cancers, in which notably higher amplification rates were observed in mCRPC studies as opposed to those sampling primary prostate cancer." (PMID 35550030, 2022). "We note that we also found peptides from LBD1 and DNMT1, but further evaluation showed that these proteins did not exhibit as strong a difference in AR-expressing prostate cancer cells, and we therefore concentrated on NFIC and TBX3, which also interacted with FOXA1 in our other RIME experiments." (PMID 35550030, 2022).
cervical cancer (5 papers, 2016 to 2025). A primary or metastatic malignant neoplasm involving the cervix. "TBX3 has been linked to breast and cervical cancer proliferation, but it also inhibits the activity of the YAP/TAZ signaling pathway involved with cellular regeneration and growth." (PMID 37895248, 2023). "In cervical cancer, the T-box transcription factor 3 (TBX3) promotes EMT, and its expression correlates with Id1 mRNA and protein levels, although it has not yet been confirmed whether TBX3 regulates Id1 directly." (PMID 41303422, 2025). "However, in HPV-positive cervical cancer, TBX3 collaborates with E6/E7 oncogenic proteins to promote cancer cell proliferation, colony formation, and migration." (PMID 38965548, 2024). "Furthermore, TBX3 is expressed in human papilloma virus (HPV)-negative cervical cancer cells and inhibits tumor proliferation and migration." (PMID 38965548, 2024).
heart failure (5 papers, 2013 to 2024). Inability of the heart to pump blood at an adequate rate to meet tissue metabolic requirements. "Of the transcription factors known or predicted to regulate HCN4 (AP1, Isl1, Mef2c, Nkx2.5, NRSF, Tbx3 and Tbx18), two (Nkx2.5 and Tbx3) did not change in the sinus node in heart failure." (PMID 32647133, 2020). "In the heart failure mice, qPCR showed no significant change in Bmp2, Bmp4, Nkx2.5, Shox2 and Tbx3 in the sinus node, but there was a significant downregulation of Tbx18 and Isl1 and upregulation of AP1, Mef2c and NRSF mRNA." (PMID 32647133, 2020). "Our GRNs highlight the importance of TBX3 in ischemic cardiomyopathy and FOXC1 in heart failure, both of which were previously associated with cardiac disorders but not specifically linked with cardiomyopathies or heart failure." (PMID 38673810, 2024).
Holt-Oram syndrome (5 papers, 2019 to 2022). Holt-Oram syndrome (HOS) is the most common form of heart-hand syndrome and is characterized by skeletal abnormalities of the upper limbs and mild-to-severe congenital cardiac defects. "TBX5 and TBX3 are required for formation and normal development of forelimbs; mutation in these genes is associated with Holt-Oram syndrome." (PMID 36360176, 2022). "Mutations within the TBX3 and TBX5 genes provide an embryologic basis for the prevalence of atrial and/or ventricular septal defects in patients with Holt-Oram syndrome." (PMID 35698674, 2022). "In humans, these heterozygous conditions can lead to syndromes, including Holt-Oram Syndrome (HOS, TBX5), ulna mammary syndrome (UMS, TBX3), DiGeorge syndrome (TBX1), spondylocostal dysostosis (TBX6) and cleft palate and ankyloglossia (TBX22)." (PMID 32855167, 2020).
Obesity (5 papers, 2017 to 2023). Accumulation of substantial excess body fat. "Other hypertension-associated genes impacted by obesity included Podxl and Ebf1 upregulated in lung art ECs, Nbeal1 and Tbx3 upregulated in heart art ECs and Igfbp3 with reduced expression in heart, kidney and brain art ECs." (PMID 36400935, 2022). "For example, miR-204 targets sirtuin 1 (SIRT1) to promote adipogenesis, while miR-93 regulates obesity by inhibiting sirtuin 7 (Sirt7) and T-box 3 (Tbx3)." (PMID 32722316, 2020). "It was recently demonstrated in mice specifically lacking Tbx3 from POMC neurons that Pomc expression was diminished leading to hyperphagia and obesity." (PMID 35044906, 2022).
atrial fibrillation (4 papers, 2022 to 2024). A disorder characterized by an electrocardiographic finding of a supraventricular arrhythmia characterized by the replacement of consistent P waves by rapid oscillations or fibrillatory waves that vary in size, shape and timing and are accompanied by an irregular ventricular response. "Wang's study showed that Pitx2 affects two microRNAs (miR-17–92 and miR-106b-25) and indirectly regulates the expression of Shox2 and TBX3, thus causing sinus node dysfunction and increasing the susceptibility to atrial fibrillation." (PMID 35851424, 2022). "One genome-wide association studies loci with long-range chromatin conformation data identified a gene interaction network dominated by NKX2–5, TBX3, ZFHX3, and SYNPO2 L, which plays an important role in the pathogenesis of atrial fibrillation." (PMID 38765775, 2024).
cardiomyopathies (4 papers, 2023 to 2024). "TBX3 is located within the 12q24.21 locus, which harbors several other genes that have previously been linked to cardiomyopathies." (PMID 36656640, 2023).
ovarian carcinoma (4 papers, 2019 to 2024). A malignant neoplasm originating from the surface ovarian epithelium. "For instance, over-expression of TBX2 and TBX3 were reported in breast, bladder, liver and ovarian cancers." (PMID 30866410, 2019).
thyroid cancer (4 papers, 2022 to 2025). "Importantly, further analysis using dataset of Thyroid carcinoma (THCA) from The Cancer Genome Atlas (TCGA) (n = 501) revealed that TBX3 expression was positively correlated with BRAF levels, suggesting that their functional coupling is clinically important." (PMID 35332119, 2022). "As expected, further analysis revealed that TBX3 was negatively correlated with immune cell infiltration in BLCA, testicular germ cell tumors (TGCT), and thyroid carcinoma (THCA)." (PMID 39897553, 2025).
colon cancer (3 papers, 2025). "Intriguingly, inspection of published data on protein–protein interactions in colon cancer cell lines revealed that significant interactions between TBX3 and β-catenin had already been detected; we consider this an important independent validation of our study." (PMID 40343989, 2025). "Of them, 10 aging-related CpG sites were mapped to 6 genes (i.e., TNF, BICC1, TBX3, SUCNR1, NCF2, DIP2B), and the altered methylation of cg03037030 located in TNF was associated with the risk of CRC, colon cancer, and rectal cancer, with consistent effect direction." (PMID 41197401, 2025).
ductal carcinoma in situ (3 papers, 2016 to 2026). "Two different isoforms of TBX3 (TBX3iso1 and TBX3iso2) were overexpressed to evaluate cell survival/colony forming ability, growth, and invasion in the ductal carcinoma in situ-like 21NT cell line using an in vitro Matrigel model of cancer progression." (PMID 27553211, 2016).
head and neck squamous cell carcinoma (3 papers, 2012 to 2025). A squamous cell carcinoma that arises from any of the following anatomic sites: lip and oral cavity, nasal cavity, paranasal sinuses, pharynx, larynx, and salivary glands. "In addition, TBX3 can influence the development of head and neck squamous cell carcinoma by regulating the PTEN tumor-related signaling pathway." (PMID 39897553, 2025).
liposarcoma (3 papers, 2016 to 2024). A usually painless malignant tumor that arises from adipose tissue. "Our results show that TBX3 mRNA and protein levels were lower in hMSCs compared to chondro- and liposarcoma cells." (PMID 35145908, 2021).
lung adenocarcinoma (3 papers, 2018 to 2024). A carcinoma that arises from the lung and is characterized by the presence of malignant glandular epithelial cells. "The expression of TBX3 is decreased by fivefold in lung adenocarcinoma and is twofold reduced in lung squamous cell carcinoma." (PMID 38413457, 2024). "TBX5 and TBX3 were highly expressed in normal lungs, but significantly suppressed in lung adenocarcinoma." (PMID 34262872, 2021). "Our results showed that signatures from TBX3 and TBX5 are significantly anti-correlated with lung adenocarcinoma signatures from patients (p < 0.05)." (PMID 30425966, 2018).
osteosarcoma (3 papers, 2023 to 2024). A usually aggressive malignant bone-forming mesenchymal neoplasm, predominantly affecting adolescents and young adults. "Thus, the TBX3/c-Myc and/or Akt cooperation may also be responsible for osteosarcoma-like lesions occurrence in Akt/FBXW7ΔF/TBX3 mice." (PMID 38909034, 2024).
ventricular tachycardia (3 papers, 2022 to 2025). A disorder characterized by an electrocardiographic finding of three or more consecutive complexes of ventricular origin with a rate greater than a certain threshold (100 or 120 beats per minute are commonly used). "Combined Tbx3 and Tbx5 deficiency in the adult VCS led to conduction defects, including prolonged PR and QRS intervals and elevated susceptibility to ventricular tachycardia." (PMID 39257760, 2025). "Taken together, these data indicate that the conduction defect and ventricular tachycardia observed in mice with VCS-specific Tbx3:Tbx5 deletion occur prior to the onset of left ventricular dysfunction or evidence of remodeling, implying a primary origin." (PMID 39257760, 2025). "Loss of Tbx3 and Tbx5 expression in the mature VCS led to profound conduction defects, characterized by prolonged PR interval and QRS duration, increased susceptibility to ventricular tachycardia, and sudden death." (PMID 39257760, 2025). "Removal of both Tbx3 and Tbx5 from the adult VCS resulted in increased episodes of spontaneous ventricular tachycardia (VT)." (PMID 39257760, 2025). "TBX3 and TBX5 can jointly mark the cardiac conduction system, and TBX5 knockout mice show abnormal heart rates, such as sinus arrest, AV block and ventricular tachycardia." (PMID 35851424, 2022).
adenoma (2 papers, 2021 to 2024). A neoplasm arising from the epithelium. "Interestingly, three stemness/differentiation-related genes, including LRRC34, CEBPB, and TBX3, showed significant changes in their expression levels in adenoma compared to normal colon mucosa." (PMID 38670944, 2024).
atrioventricular block (2 papers, 2018 to 2022). A heart block that is initiated in the atrioventricular node. "Nevertheless, specific cuts through the Tbx3-positive bundle caused atrioventricular block, implicating the Tbx3-negative myocardial continuity between the atria and ventricles was not sufficient to maintain atrioventricular conduction." (PMID 29565246, 2018).
cardiac conduction disorders (2 papers, 2025). "Collectively, these findings indicate that Tbx3 and Tbx5 coordinate to control VCS molecular fate and function, with implications for understanding cardiac conduction disorders in humans." (PMID 39257760, 2025).
cardiac hypertrophy (2 papers, 2017 to 2023). "Genetic variation in TBX3 was associated with LV mass in healthy Japanese population, highlighting potential implications in cardiac hypertrophy; however, precise mechanisms warrant further investigation." (PMID 36656640, 2023).
congenital heart disease (2 papers, 2015 to 2019). A heart disease that is present at birth. "TBX5 is primarily linked to congenital heart disease; however, the homologs TBX2 and TBX3, which share DNA binding consensus with TBX5, are associated with cancer and invasive cellular behavior." (PMID 26549256, 2015).
developmental delay (2 papers, 2013 to 2021). "Thus, developmental delay is associated with the Tbx3 mutant genotype, even though Tbx20 mutants have a more severe and earlier heart abnormality." (PMID 23936153, 2013). "Haploinsufficiency of the syntenic region containing TBX3 and MED13L has been reported to cause short stature, developmental delay, and intellectual disability, among other conditions in humans, and is established as a major contributor to height in horses." (PMID 33863806, 2021). "Among the embryos from Tbx20+/-; Tbx3+/- double heterozygous crosses at E8.5, some single or double homozygous embryos showed developmental delay, but over 90% were living (65/71); by E9.25, however, 37% (7/19) were dead." (PMID 23936153, 2013).